TET2 (tet methylcytosine dioxygenase 2)
Diseases named in the same sentence as TET2 in open-access papers (continued):
Sharing a sentence is not in itself a finding about the gene and the disease.
cancer (continued). "Among nine cancer-associated mutations that determine sensitivity to ATRA (Notch 1, BCR_ABL, KIT, FLT3, APC, TET2, K-ras, ALK, MLL_AFF1), KRAS, APC, and KIT mutations are associated with resistance to ATRA (only K-ras is shown)." (PMID 23982413, 2013). "Our findings identify EBF1 as novel interaction partner of TET2, confirm IDH mt-mediated hypermethylation to be a recurrent phenomenon in unrelated types of cancer, and have identified tissue- and cancer- specific effectors as key drivers, and potential therapeutic targets." (PMID 23863747, 2013). "Future experiments may seek to test whether altered α-ketoglutarate or 2HG concentrations can affect HIF-1a or TET2 pathway members in vitro, and identify the cellular pathways necessary for the IDH mutants to exert a cancer-related phenotype." (PMID 21326614, 2011). "Based on the synergy between TET2 to IL-2/STAT5A signaling, we further examined whether VC enhanced the efficacy of anti-PD-L1 and IL-2 combination therapy, which is a potentially promising candidate for cancer therapy." (PMID 38177099, 2024). "TET2-mediated cGAS expression may be cancer cell-specific, as VC exposure has no obvious effect on cGAS expression in endothelial cells." (PMID 38177099, 2024). "In solid tumors, TET2 loss-of-function mutations are not commonly observed; however, TET enzymatic activity is often low, consistent with an overall low level of genomic 5hmC in some cancers." (PMID 39388288, 2024). "Recent studies demonstrated that TET2 mediated the alterations of 5-hmC in response to glucose in ECs, as TET1 and TET3 were barely detectable in ECs, and TET2 could be regulated by hypoxia in some cancer cell lines." (PMID 36658614, 2023). "Therefore, this study aimed to comprehensively analyze the clinical significance of TET2 in major female cancers, which, to the best of our knowledge, has never been reported previously." (PMID 35223782, 2022). "Whether TET2 participates in immune checkpoint suppression mediated by the CTLA-4 or PD-1 pathway, whether and how TET2 acts on CD8+ cytotoxic T lymphocytes, and coordination of PD-L1/CTLA-4 to regulate the anti-cancer CD8+ T-cell response remain to be studied further." (PMID 35223782, 2022). "However, the lack of complete phenotypic overlap between IDH1 mutant and TET2 mutant cancers suggests that IDH1 can modulate leukemogenesis independently of TET2." (PMID 33805247, 2021). "Tet2/3fl/flFoxp3Cre mice lacking Tet2 and Tet3 in Treg cells develop inflammatory disease, and Treg cells from these mice show altered expression of Treg signature genes and upregulation of genes involved in cell cycle, DNA damage and cancer." (PMID 31043609, 2019). "Moreover, mutations of FBWX7, ERBB2, TET2, BCL2L1, NOTCH1, FGFR1 and TSC1 were only detected in patients without germline cancer-associated variants." (PMID 30850667, 2019). "Using mouse models, we and other groups have shown that deletion of Tet2 alone, or deletion of both Tet2 and Tet3 (the two TET enzymes with the greatest overlap in expression and function), leads to myeloid or lymphoid expansion and the development of aggressive cancers with 100% penetrance." (PMID 30809228, 2019). "Our data support the hypothesis that a lack of glutamine forces the selection of an epigenetic state that does not require a high level of TET2, thus selecting an “undifferentiated” therapy-resistant phenotype as seen in TET2-mutant cancers." (PMID 31217902, 2019). "To further investigate whether the RCMS dCasRx-Tet2 CD editor could induce a decrease in m5C level and impact the invasive and metastatic phenotype in cancer cells, we transduced HepG2 cells with dCasRx-Tet2 CD with gRNA 0 nt or nontarget gRNA using a lentivirus system." (PMID 38366553, 2024).
cancer (continued). "Using the Pan-Cancer TCGA dataset gathering RNA-seq data from 11,060 patients, an anticorrelation between TET2 expression and mRNA levels of lysosome proteins was confirmed for CLN3, CTSD, CTSF, CTSZ, IFI30, and NAGLU, suggesting TET2 might down-regulate lysosomal genes in various types of cancer." (PMID 35351824, 2022). "Unlike other signaling pathways involved in cancer progression, such as ERK signaling, p-AKT was up-regulated considerably in Huh 7 cells after TET2 knockdown." (PMID 36732324, 2023). "In multiple cancer cell lines and primary tumors, whole genome CpG methylation analysis showed that TET1, but not TET2 or TET3, was downregulated by promoter methylation compared to the normal controls." (PMID 34209564, 2021). "In summary, by exploring the signaling pathways unique to HCC and absent from other types of cancer, we demonstrated, for the first time, that FGFR3∆7–9 phosphorylates the tumor suppressor TET2 at Y1902, which promotes TET2 ubiquitination and destruction." (PMID 33097695, 2020). "Interestingly, by analyzing other types of cancer cell lines from CCLE, we found that at least two other kinds of cancer types (lung and soft tissue) had a significant negative correlation between TET2 and PD-L1 mRNA expression levels." (PMID 34064441, 2021).
hematological malignancies (97 papers, 2012 to 2026). "Mutations in genes like ASXL1 and TET2 are often mutated in the elderly and are associated with clonal hematopoietic expansion, with a high risk of developing hematologic malignancies." (PMID 41514668, 2026). "In hematological malignancies, the prognostic implications of 5hmC are further shaped by the mutational status of TET2." (PMID 41243111, 2025). "Over half of the TET2 mutations in hematological malignancies occur in those of a myeloid lineage (65%), with the remaining 35% occurring in lymphoid disease." (PMID 40116537, 2025). "Recent studies identified TET2 mutations as one of the highly prevalent among various hematological malignancies and clonal hematopoiesis of indeterminate potential (CHIP)." (PMID 41169875, 2025). "We also noted that PROSER1 alterations, including missense, splice site, and frameshift mutations, have been identified in various hematological malignancies of both myeloid and lymphoid origin, albeit at much lower frequencies than TET2 mutations." (PMID 40554416, 2025). "Recent studies have shown that hematological disorders with TET2 mutations can exacerbate other diseases." (PMID 40599235, 2025). "Although genes encoding TET1 and TET3 are rarely mutated in hematopoietic diseases, TET2 frequently undergoes somatic mutation, affecting both lymphoid and myeloid lineages." (PMID 36675240, 2023). "In this cohort, all 12 CMML patients carried not only TET2 mutations but also mutations in other genes commonly affected in hematological disorders." (PMID 37267914, 2023). "Somatic pathogenic variants of TET2 have been reported from patients with various hematologic malignancies." (PMID 37325673, 2023). "Mutations in the TET2 gene predispose to hematological malignancies by causing DNA methylation overload and aberrant epigenomic landscape." (PMID 36639817, 2023). "The first cohort at the University College London Hospital (UCLH) cohort was composed of 22 patients with a different degree of hematological disorders (from CH to MDS) that only carry mutations in the TET2 gene." (PMID 37267914, 2023). "In particular, the loss of DNMT3A and TET2 function is conspicuous in diverse hematological disorders, including myeloid and lymphoid malignancies, and causally related to clonal hematopoiesis and malignant transformation." (PMID 36675240, 2023). "Loss-of-function TET2 mutations are one of the most common and prevalent mutations found in CH scenarios and constitute a risk factor for the development of hematological malignancies." (PMID 37267914, 2023). "To validate these observations in primary human samples, we obtain data from two independent cohorts of human patients previously diagnosed with hematological diseases carrying TET2 mutations." (PMID 37267914, 2023). "Out of 612 patients who underwent NGS of 34 recurrently mutated genes in haematological diseases, 100 haematological patients with TET2 mutations were selected for further study." (PMID 35279121, 2022). "Although our study is the first to report the role of germline TET2 mutations in haematological diseases, there are still many limitations." (PMID 35279121, 2022). "Although less often occurred in lymphoid malignancies, TET2 mutations were reported as age-related in other hematological malignancies." (PMID 35401516, 2022). "This heightened interest was sparked by the discovery that a TET2 mutation was associated with the development of hematological malignancies through its regulatory role in lineage commitment." (PMID 35456443, 2022). "The Ten-Eleven Translocation-2 (TET2) gene, located on chromosome 4q24, has been implicated in hematological malignancies." (PMID 34660059, 2021). "Patients with hematological malignancies who also have Tet2 mutations or loss of function are more likely to develop autoimmune and autoinflammatory diseases than those without Tet2 mutations, and these abnormalities can even cause various tumors." (PMID 34222235, 2021).
hematological malignancies (continued). "In hematological malignancies, loss-of-function mutations of TET2, which is one of the TET family genes including TET1, are frequently found, while the mutations of TET1 are not." (PMID 33705482, 2021). "This survival analysis indicates that harboring two or more pathological mutations in TET2 with relatively high allele burden (>15%) is an independent risk factor to predict the second hematologic malignancies in AITL patients." (PMID 34581268, 2021). "Several previous studies have reported that genetic variants in the TET2 gene are involved in development of hematological malignancies including AML." (PMID 33643703, 2021). "Even though hematologic malignancies present the most interest regarding TET2 mutations, the literature also contains data regarding the presence of TET2 mutations in other malignancies." (PMID 33805247, 2021). "The report of Chiba showed that the mutation of TET2 is closely related to the initiation of hematologic malignancies." (PMID 33146288, 2020). "Among the three TET family members, TET2 shows a strong expression in hematopoietic lineage and undergoes somatic mutations frequently in hematological malignancies." (PMID 31527484, 2019). "An especially high expression of TET2 has been found in hematopoietic tissues suggesting it has an important role to play in this process, which is supported by the fact that TET2 is frequently mutated in hematological malignancies." (PMID 29899831, 2018). "TET2 mutation occurs early in leukemogenesis, suggesting its significance in the onset and progression of hematologic malignancies." (PMID 28039446, 2017). "Mutations that disrupt the catalytic domain or lead to a truncated TET2 have been linked to the development of hematological malignancies." (PMID 28505169, 2017). "A survey of TET2 mutations in the COSMIC database showed more deleterious mutations in hematological malignancies than in solid tumors (29.8% versus 7.3% for frameshift mutations and 28.1% versus 10.3% for nonsense mutations)." (PMID 25632305, 2015). "By combining our data with public databases, we supposed that germline TET2 mutations have a family aggregation in haematological diseases and that patients with germline TET2 mutations may be younger." (PMID 35279121, 2022). "Furthermore, we compared its impact in haematological diseases with somatic TET2 mutations, including their mutation sites, variant allele frequency (VAF), diagnosis distributions, blood cell counts, prognosis, and survival." (PMID 35279121, 2022). "TET2 was found to be involved in the regulation of genes associated with self-renewal and differentiation in hematopoietic stem cells, and mutations in TET2 have been associated with hematological malignancies." (PMID 35563709, 2022). "Furthermore, the prognosis of TET2 mutation in hematologic malignancies has been controversial, and the detailed mechanism of TET2 in the promotion of malignancy needs to be further explored." (PMID 35456443, 2022). "The strong association of DNA hypermethylation coupled with the frequent mutation of TET2 in hematological malignancies suggest that vitamin C treatment could be a targeted therapy for these patients." (PMID 34017357, 2021). "Furthermore, we found that CH associated with multiple-hit TET2 (defined as ≥2 pathogenic TET2 mutations with VAFs of ≥15%) is an independent risk factor for development of concurrent hematologic malignancies in AITL patients." (PMID 34581268, 2021). "Although mutations in epigenetic factors like DNMT1/3a and TET2 are common in hematological malignancies, there are mixed findings when it comes to whether such genetic alterations are principal contributors to secondary resistances." (PMID 34358067, 2021). "Interestingly, TET2 mutations, which is frequently found in hematologic malignancies, was also found in all cases of p.Gly17Val RHOA mutation, suggesting a strong correlation between RHOA and TET2 dysfunctions." (PMID 33406731, 2021).
hematological malignancies (continued). "Remarkably, TET2 is frequently mutated in hematological malignancies." (PMID 32726753, 2020). "Furthermore, the prognosis of TET2 mutation in hematologic malignancies has been controversial and the detailed mechanism of TET2 in promotion of malignancy needs to be further explored." (PMID 31001476, 2019). "For example, the decreased expression of TET2 and the decrease of 5hmC content caused by the abnormal expression of miR-22 may be another important reason for hematological malignancies and solid malignancies in addition to the TET2 mutation." (PMID 31656200, 2019). "TET2 mutations, as an early event in pathogenesis, may cooperate with other gene mutations, deemed background mutations, to promote various hematological malignancies." (PMID 31001476, 2019). "In addition to hematologic malignancies, the dysregulation of TET2 or 5-hmC has been implicated in the carcinogenesis of several solid tumors." (PMID 27050164, 2016). "Moreover, a loss-of-function mutation in the TET2 gene is associated with hematological malignancies, and mutations in the three TET genes are related to solid tumors." (PMID 26207381, 2015). "In mouse models, loss of one or both copies of Tet2 has been shown to contribute to the pathogenesis of hematological malignancies by increasing the self-renewal capacity of the hematopoietic stem cell compartment and expanding the immature pool of myeloid and lymphoid progenitors." (PMID 24788138, 2014). "In particular, several authors showed that vitamin C may be a useful anti-leukemic agent able to restore the dioxygenase activity, thereby attenuating the effects of TET2 dysfunction, a widespread feature of hematological malignancies beyond the mere presence of mutations." (PMID 35832559, 2022). "Therefore, whether germline and somatic TET2 mutations have different effects on the prognosis of patients with haematological disease is still ambiguous." (PMID 35279121, 2022). "Previous research has shown that ITP patients harboring mutations in genes such as DNMT3A, TET2, ASXL1, BCOR, PIGA, and U2AF1 tend to progress into other clonal hematologic disorders, leading to treatment ineffectiveness." (PMID 40574285, 2025). "MBD6 promoted a more open chromatin state and increased transcription in stem cells in malignancies with TET2 depletion, suggesting a potential therapeutic avenue for targeting TET2‐mutant hematological malignancies via the development of MBD6 inhibitors." (PMID 40116537, 2025). "Among these, TET2 mutations emerged as a common feature, present in BPDCN and the associated hematologic malignancies in 9 of the 10 patients." (PMID 41451201, 2025). "The advances in genomics, transcriptomics, proteomics, and metabolomics present a new opportunity to study the biological aspects of TET2 with haematological disorders, especially VTE." (PMID 41169875, 2025). "When linked to somatic mutations in myeloid malignancy-associated genes, such as TET2-mediated clonal hematopoiesis of indeterminate potential or CHIP, it represents increased risk for hematological malignancies and cardiovascular disease." (PMID 38062031, 2023). "The result is promising as TET2-mediated demethylation specifically at enhancer regions is known to play important roles in development, cell differentiation, and hematological disease." (PMID 36639817, 2023). "CH is typically defined by pathogenic driver mutations associated with hematological malignancies, most commonly in the epigenetic regulators DNMT3A, TET2, and ASXL1, which collectively account for 90% of CH cases." (PMID 37083525, 2023). "Somatic mutations in TET2 are frequently identified in individuals with CHIP and various lymphoid and myeloid hematological malignancies." (PMID 38028538, 2023). "In contrast, TET2-mutated NK-LGLL exhibit a CD16low phenotype and are associated with a low platelet count and the coexistence of other hematologic malignancies." (PMID 36358655, 2022).